RAB34 (RAB34, member RAS oncogene family)
Description:
The small GTPases Rab are key regulators of intracellular membrane trafficking, from the formation of transport vesicles to their fusion with membranes. Rabs cycle between an inactive GDP-bound form and an active GTP-bound form that is able to recruit to membranes different sets of downstream effectors directly responsible for vesicle formation, movement, tethering and fusion (By similarity). RAB34 transports protein involved in the redistribution of lysosomes to the peri-Golgi region. Plays a role in the maturation of phagosomes that engulf pathogens, such as S.aureus and M.tuberculosis. Plays a role in the fusion of phagosomes with lysosomes. Involved in ciliogenesis. In particular, it is required for early steps of the intracellular cilium assembly pathway initiated by trafficking and docking of ciliary vesicles to the centrioles in the cytoplasm, followed by axoneme formation in the cytoplasm. After axoneme elongation, the centrioles migrate close to the cell surface so that ciliary vesicles can fuse with the plasma membrane to expose cilia to the extracellular space (By similarity). It seems dispensable for ciliogenesis via the extracellular pathway where cilium assembly begins after migration and docking of the centriole to the plasma membrane (By similarity). Also acts as a positive regulator of hedgehog signaling and regulates ciliary function (By similarity).
Synonyms: NARR; RAB39; RAH; OFD20
Tractability: PROTAC: its protein half-life has been measured.
Gene: Protein-coding gene on chromosome 17 (28,713,545 to 28,719,594, reverse strand). Ensembl gene ENSG00000109113.
Subcellular location: Nucleus; Nucleus, nucleolus; Cytoplasm; Golgi apparatus; Cytoplasmic vesicle, phagosome; Cytoplasmic vesicle, phagosome membrane; Cell projection, cilium; Cytoplasm, cytoskeleton, microtubule organizing center, centrosome; Cytoplasm, cytoskeleton, microtubule organizing center, centrosome, centriole
Subcellular location (Human Protein Atlas): Nucleoplasm; Primary cilium; Basal body; Centrosome; Cytosol
Pathways (Reactome):
Metabolism of proteins: RAB geranylgeranylation
Gene Ontology:
Molecular function: GTP-dependent protein binding; protein binding; small GTPase binding; G protein activity; GTP binding; GTPase activity
Biological process: antigen processing and presentation; cilium assembly; Golgi to plasma membrane protein transport; lysosome localization; macropinocytosis; phagosome maturation; phagosome-lysosome fusion; protein localization to plasma membrane; cytosolic ciliogenesis; positive regulation of smoothened signaling pathway
Cellular component: centriole; centrosome; extracellular exosome; Golgi apparatus; Golgi cisterna; Golgi stack; nucleoplasm; perinuclear region of cytoplasm; phagocytic vesicle; ruffle membrane; vesicle; cytoplasm; cilium; phagocytic vesicle membrane
Genetic constraint (gnomAD): Loss-of-function variants: 34 observed, 39.3 expected, observed/expected ratio (o/e) 0.87, 90% interval 0.66 to 1.15. The upper end of that interval is the gene's LOEUF score, 1.15, which puts it in group 5 of 6, group 1 being the genes least tolerant of losing a copy. Missense variants: 289 observed, 336.13 expected, observed/expected ratio (o/e) 0.86, 90% interval 0.78 to 0.95. Synonymous variants: 135 observed, 129.62 expected, observed/expected ratio (o/e) 1.04, 90% interval 0.9 to 1.2.
Homologues: Orthologues: macaque RAB34 (99% identical), guinea pig RAB34 (97% identical), pig RAB34 (97% identical), mouse Rab34 (95% identical), dog RAB34 (92% identical), rabbit RAB34 (90% identical), rat Rab34 (89% identical), tropical clawed frog rab34 (80% identical), chimpanzee RAB34 (75% identical), zebrafish rab34a (75% identical). Paralogues in human: RAB36 (58% identical), RAB1A (30% identical), RAB1B (30% identical), RAB13 (28% identical), RAB11B (27% identical), RAB33A (27% identical), RAB11A (26% identical), RAB33B (26% identical), RAB35 (26% identical), RAB37 (26% identical), RAB39A (26% identical), RAB23 (25% identical), and 56 more.
Diseases named in the same sentence as RAB34 in open-access papers:
RAB34 is named in the same sentence as 18 diseases in open-access papers, as found by Europe PMC text mining. Sharing a sentence is not in itself a finding about the gene and the disease. The quoted sentences say what the papers report.
glioma (5 papers, 2019 to 2024). A benign or malignant brain and spinal cord tumor that arises from glial cells (astrocytes, oligodendrocytes, ependymal cells). "Subsequently, receiver operating characteristic (ROC) analysis was employed to explore the diagnostic significance of RAB34 as a signature for diagnosing IDH status in glioma." (PMID 36222286, 2022). "Considering the GO analysis data, we next investigated whether RAB34 expression was linked to the infiltrated cells in glioma using ESTIMATE algorithm method described by Yoshihara." (PMID 36222286, 2022). "However, the underlying function, as well as the mechanism of RAB34 in the progression of glioma remain unclear." (PMID 36222286, 2022). "Interestingly, RAB38, a new member of the RAB small G protein family that regulates intracellular vesicle trafficking, RAB27a, as well as RAB34 have all been reported to confer a poor prognosis, associated with malignant progression and subtype preference in gliomas." (PMID 36430705, 2022). "In conclusion, this study discovered a novel function for RAB34 in enhancing the malignant phenotype and resulting in immune evasion of glioma." (PMID 36222286, 2022). "We established that IDH wild-type glioma exhibited a higher content of RAB34 in contrast with IDH mutant glioma in TCGA and CGGA datasets." (PMID 36222286, 2022). "Taken together, these results indicated that RAB34 played an important role in the inflammatory response in glioma." (PMID 36222286, 2022). "Herein, we assessed the expression and immune features of RAB34 in glioma at the molecular, as well as clinical levels via a large-scale analysis, and further investigated the biological role of RAB34 via in vitro experiments." (PMID 36222286, 2022). "Herein, we comprehensively analyzed the oncogenic role of RAB34 in the malignant progress of glioma by conducting a large-scale analysis and in vitro experiments." (PMID 36222286, 2022). "The data demonstrated that the expression of RAB34 was not only aberrantly overexpressed in glioma but also dramatically correlated with WHO grade." (PMID 36222286, 2022). "The data illustrated that RAB34 expression was dramatically increased in glioma samples than that in normal brain tissues." (PMID 36222286, 2022). "To further confirm these results, we examined RAB34 expression level in glioma samples, as well as cell lines via qRT-PCR." (PMID 36222286, 2022). "In multivariate analysis, RAB34 expression was still a remarkable prognostic factor after correcting for other clinical factors, such as age, gender, and glioma grade." (PMID 36222286, 2022). "To further investigate the possible mechanism of high RAB34 levels in glioma, we integrated TCGA glioma datasets and identified 594 patients with RAB34 expression along with DNA methylation data." (PMID 36222286, 2022). "Our findings established RAB34 as a novel progression-related biomarker and a possible immunotherapy target for glioma." (PMID 36222286, 2022). "A profound comprehension of the expression and feature of RAB34 would provide a molecular basis for the future immunotherapy of glioma." (PMID 36222286, 2022). "However, our study only demonstrated a correlation between RAB34 expression and DNA methylation, more in-depth experiments are needed to verify whether the increased expression of RAB34 is directly caused by DNA methylation in glioma." (PMID 36222286, 2022). "In vitro experiments demonstrated that inhibition of RAB34 restrained the growth, migration, as well as invasion of glioma cells, and reversed the epithelial-to-mesenchymal transition (EMT) process." (PMID 36222286, 2022). "Bioinformatics and PCR analysis showed that RAB34 expression was positively related to the glioma tumor grade and predicted poor outcomes for glioma patients." (PMID 36222286, 2022). "In this context, expression levels of ARP2/3 and RAB34 correlate with the grade of the tumor and/or the survival of the patient, with both being upregulated from low-grade to high-grade gliomas." (PMID 30909495, 2019).
glioma (continued). "Besides, the increased expression, RAB34 was positively correlated with advanced WHO grade of glioma." (PMID 36222286, 2022). "In summary, RAB34 was an independent predictive factor for patients with glioma." (PMID 36222286, 2022). "Furthermore, we verified that the expression of RAB34 was significantly increased after treatment with DAC in glioma cell lines." (PMID 36222286, 2022). "In addition, CCK-8 assays showed that the viability of glioma cells was remarkably reduced after knockdown of RAB34." (PMID 36222286, 2022). "Simultaneously, we performed univariate and multivariate analyses to explore whether RAB34 could be an independent predictive factor for glioma patients." (PMID 36222286, 2022). "Our results illustrated that RAB34 was highly enriched in IDH wild-type glioma." (PMID 36222286, 2022). "Additionally, RAB34 expression was significantly up-regulated in classical and mesenchymal subtypes, and isolated diastolic hypertension wild-type gliomas." (PMID 36222286, 2022). "Furthermore, our research certified that RAB34 was an independent predictive marker for individuals with glioma." (PMID 36222286, 2022). "Considering that RAB34 expression is abnormally expressed in glioma and correlates with histological grade, as well as molecular subtype, we speculated that RAB34 may be an indispensable prognostic signature for glioma patients." (PMID 36222286, 2022). "Furthermore, we conducted Western blot assays to assess the influence of RAB34 on the EMT process in glioma cells." (PMID 36222286, 2022). "Our findings highlighted the potential of RAB34 as a novel immunotherapeutic target for glioma." (PMID 36222286, 2022). "Our results indicated that hypomethylation of RAB34 promoter region may be a key contributor to the increased RAB34 expression in glioma." (PMID 36222286, 2022). "Moreover, RAB34 expression was remarkably correlated with inflammatory activities, immune infiltration, and immune checkpoints in glioma." (PMID 36222286, 2022). "In summary, these data implied that RAB34 expression was possibly modulated by promoter DNA methylation, and this epigenetic modification could also serve as a promising prognostic signature for patients with glioma." (PMID 36222286, 2022). "Furthermore, RAB34 promoted the proliferation, migration, and infiltration of glioma cells." (PMID 36222286, 2022). "Herein, we found that RAB34 expression was remarkably related to EMT markers and promoted EMT process in glioma." (PMID 36222286, 2022). "Intriguingly, RAB34 exhibited closely positive relationship with these immune checkpoints (PD-1, PD-L1, CTLA4, PD-L2, TIM-3, and B7-H3) in all grade gliomas in TCGA and CGGA cohorts as shown by Circos plots." (PMID 36222286, 2022). "We found that RAB34 expression was remarkably higher in GBM (WHO IV) in contrast with that in WHO grade II, as well as grade III gliomas." (PMID 36222286, 2022). "Moreover, RAB34 expression was up-regulated in U251, U87, A172, H4, and SHG44 glioma cells than that in HA1800." (PMID 36222286, 2022). "In addition, high RAB34 expression predicted a worse prognosis, which is consistent with its enrichment in IDH wild-type glioma." (PMID 36222286, 2022).
breast carcinoma (3 papers, 2015 to 2024). "A recent study has found that RAB34 is overexpressed in breast cancer and that the high expression of RAB34 is closely linked to breast cancer cell adhesion, migration, and invasion." (PMID 34917619, 2021). "RAB34 (ENSG00000109113) regulates the spatial distribution of lysosomes, secretion, and micropinocytosis and is expressed at high levels in breast cancer cell lines." (PMID 34917619, 2021).
ciliopathies (2 papers, 2021 to 2025). "Additionally, loss-of-function variants of Rab34 are associated with various ciliopathies, suggesting the possibility that dysregulation of Rab34-mediated Golgi-lysosome interactions may contribute to the pathogenesis of human diseases." (PMID 40134576, 2025). "In the absence of Rab34, primary cilia formation by both cultured cells and in vivo was found to be inhibited, and another independent study by the IMPC has shown that Rab34‐KO mice exhibit typical ciliopathy phenotypes, including polydactyly and craniofacial malformation." (PMID 32542850, 2021).
gastric carcinoma (2 papers, 2009 to 2013). A carcinoma that arises from epithelial cells of the stomach. "Meanwhile, we confirmed that RAB34, GRB2 were down regulated by miR-9 and miR-433 respectively, which revealed the potential mechanism for gastric carcinoma genesis." (PMID 19531230, 2009).
lung carcinoma (2 papers, 2017 to 2026). "In contrast, TSG101, involved in lung cancer cell proliferation, RAB34, HYOU1 and ACOT1 showed higher expression in AC, as compared to their levels in SCC." (PMID 29285267, 2017). "Knockdown of Rab34 in neutrophils dramatically attenuated LDEs-induced lipid accumulation, fatty acid β-oxidation activation, and NETs formation, thereby mitigating neutrophil-involved lung cancer progression in vivo." (PMID 42125308, 2026).
melanoma (2 papers, 2022 to 2023). A malignant, usually aggressive tumor composed of atypical, neoplastic melanocytes. "According to TCGA analysis data, RAB34 expression is increased in high-grade glioblastoma compared to lower grades, and UBTF is increased in melanoma compared to normal skin." (PMID 37689310, 2023). "From other validated targets in this study that have not yet been investigated in melanoma, we would like to point out MRAS, IL1R2, RAB34, LAPTM5, RDH10, and STK32C." (PMID 36139698, 2022).
kidney cancer (1 paper, 2016). Primary or metastatic malignant neoplasm involving the kidney. "Taken together, these data are strongly supportive of a DENN domain‐dependent role for FLCN regulation of lysosome distribution through a Rab34/RILP axis in BHD kidney cancer cells." (PMID 27113757, 2016).
non-small cell lung carcinoma (1 paper, 2024). A group of at least three distinct histological types of lung cancer, including non-small cell squamous cell carcinoma, adenocarcinoma, and large cell carcinoma. "For example, recent studies have found that RAB34 was downregulated in CRC but upregulated in the non-small cell lung cancer when compared with nonmalignant tissues." (PMID 38608841, 2024).
Obesity (1 paper, 2024). Accumulation of substantial excess body fat. "Finally, Rab34 levels in the adipose tissue and adipocytes are regulated in response to obesity and related pathogenic insults (i.e., fibrosis)." (PMID 38183057, 2024). "Together, these observations suggest that obesity-related insults may modify Rab34 association with LDs." (PMID 38183057, 2024). "Further studies are needed to fully establish the protein traffic routes to LDs in adipocytes as well as to unveil whether other obesity-associated insults may differentially regulate Rab34 distribution at ERGIC, ERES and LDs." (PMID 38183057, 2024). "Analysis of published data from transcriptomic studies of human abdominal SC fat samples showed that Rab34 transcript content is higher in individuals with obesity than in lean individuals." (PMID 38183057, 2024). "To this end, we analyzed Rab34 localization in mature adipocytes isolated from OM and SC samples obtained from individuals with obesity during bariatric surgery procedures." (PMID 38183057, 2024). "Rab34 dysregulation in obesity may contribute to the altered adipokine secretion and lipid metabolism that characterize adipocyte dysfunction in conditions of excess adiposity." (PMID 38183057, 2024). "According to our current data in adipocytes cultured in 3D microgels mimicking the fibrotic microenvironment of the SC in the context of obesity, it is tempting to speculate that Rab34 traffic through ERES and/or ERGIC is disrupted under these conditions." (PMID 38183057, 2024). "We also evaluated Rab34 expression in different murine models of obesity." (PMID 38183057, 2024). "In this scenario, dysregulation of Rab34 levels and/or localization, as demonstrated herein for obesity conditions, could contribute, at least in part, to both the changes in the secretory profile and impaired lipid metabolism that characterize adipocyte dysfunction in obesity." (PMID 38183057, 2024). "Finally, Rab34 regulation in response to obesity was also evaluated." (PMID 38183057, 2024). "Finally, based on the results obtained in human and animal models, we wanted to test whether, in addition to changes in Rab34 content, the localization of this GTPase may be also affected under obesity conditions." (PMID 38183057, 2024). "Culture of 3T3-L1 adipocytes in COL-I-based 3D microgels enriched in the proteoglycan, lumican (i.e., obesity conditions), induced a decrease in the number of LDs immunostained for Rab34, though no changes were observed in total Rab34 immunosignal per cell." (PMID 38183057, 2024).
ovarian carcinoma (1 paper, 2024). A malignant neoplasm originating from the surface ovarian epithelium. "This raises the possibility of RAB34 playing a part in the inherent resistance mechanism of this ovarian cancer variant." (PMID 39702158, 2024).
serous ovarian cancer (1 paper, 2024). "There's a scholarly accord that in specific paclitaxel-resistant serous ovarian cancer samples, miR-9 expression was diminished, and intriguingly, RAB34 was pinpointed as its direct influencer." (PMID 39702158, 2024).
cancer (8 papers, 2008 to 2025). A tumor composed of atypical neoplastic, often pleomorphic cells that invade other tissues. "NARR, an isoform of RAB34, is small GTPases involved in protein transport and is associated with many cancers." (PMID 38608841, 2024). "RAB34, a type of RAB proteins, has been documented to be expressed abnormally and play critical roles in diverse kinds of cancer." (PMID 36222286, 2022). "RAB34 (RAB34, member RAS oncogene family) is aberrantly expressed in various cancers and exhibits oncogenic properties." (PMID 36222286, 2022). "Interestingly, both RAB34 and UBTF were recently found to be involved in cancer development." (PMID 37689310, 2023).
tumor (6 papers, 2013 to 2022). "In GC, miR-9 has been reported to be mainly downregulated, functioning as a tumor suppressor by targeting RAB34 (encoding the Ras-related protein RAB-34) and NFKB1 (encoding the NF-kappa-B transcription factor) oncogenes." (PMID 29879907, 2018). "Interestingly, though the mRNA level of RAB34 was downregulated in tumor tissues, a high level of RAB34 was significantly associated with poor OS and DFS." (PMID 35154286, 2022). "Our immunohistochemistry analysis showed strong staining signals of RAB34 in CRC tumor tissues but low in normal tissues." (PMID 35154286, 2022). "We established that RAB34 was remarkably up-regulated in malignant glioma and was related to immune infiltration and tumor progression." (PMID 36222286, 2022). "Recent investigations revealed that RAB34 participated in tumor oncogenesis and progression of multiple cancers." (PMID 36222286, 2022). "Overexpression of RAB34 may lead to poor prognosis and tumor progression for patients with liver cancer." (PMID 36222286, 2022). "We also found that several other key actors of macropinocytosis, such as Rab34, Arp2/3 complex and SWAP70, were significantly overexpressed according to the grade of the tumor (Table A1)." (PMID 30909495, 2019).
RAB34 also shares sentences with these, for which no sentence is quoted: infection (2 papers); glioblastoma (1); hepatocellular carcinoma (1); prostate carcinoma (1); Salmonella Infections (1).